S100A6 (S100 calcium binding protein A6)
Diseases named in the same sentence as S100A6 in open-access papers (continued):
Sharing a sentence is not in itself a finding about the gene and the disease.
congestive heart failure (1 paper, 2018). Failure of the heart to pump a sufficient amount of blood to meet the needs of the body tissues, resulting in tissue congestion and edema. "We noted increased SNO modification (–ve RoR value) of three proteins (THBS1, S100A6, abd SH3BGRL2) in ChD patients in this study, as well in congestive heart failure (CHF) patients of idiopathic etiology in a previous study." (PMID 30697201, 2018).
dry eye (1 paper, 2015). "Different proteins involved with dry eye dysfunction: ANXA1, ANXA11, CST4, PRDX5, PLAA and S100A6; were validated as biomarkers." (PMID 26287192, 2015).
dyslipidemia (1 paper, 2022). "Interestingly, the multivariate logistic regression analysis confirmed that dyslipidemia did not contribute to the observed differences, and therefore the differences observed for MT1A, S100A6, LF, Fe and Cu are as result of AMD disease." (PMID 35426907, 2022).
esophageal cancer (1 paper, 2025). A primary or metastatic malignant neoplasm involving the esophagus. "Our study reveals that inhibition of S100A6 can significantly reduce the DDR capability of radiation‐resistant cells in esophageal cancer, while also suppressing the NHEJ and HR repair pathways." (PMID 39375892, 2025).
Granuloma (1 paper, 2024). A compact, organized collection of mature mononuclear phagocytes, which may be but is not necessarily accompanied by accessory features such as necrosis. "Similar findings were seen for S100a6, which localized around granulomas and portal tracts." (PMID 38562583, 2024).
Hyperglycemia (1 paper, 2022). An increased concentration of glucose in the blood. "Another study indicated that S100A6 could specifically promote calcium-stimulated insulin release, which is associated with hyperglycemia." (PMID 35432196, 2022).
injury (1 paper, 2017). Damage inflicted on the body as the direct or indirect result of an external force, with or without disruption of structural continuity. "Interestingly, low levels of S100A6 protein and mRNA have been observed in rat models of traumatic brain injury, which is associated with reduced levels of glucocorticoid receptors in the hippocampus." (PMID 28068373, 2017).
intestinal tumor (1 paper, 2025). "Our analysis results show that S100A6 and CLU exhibit high expression in intestinal tumor tissue." (PMID 41009818, 2025).
invasive breast carcinoma (1 paper, 2023). A carcinoma that infiltrates the breast parenchyma. "This study revealed that S100A6 was highly expressed in 51% of invasive breast cancer patients (among 107 cases)." (PMID 37217945, 2023). "For patients with invasive breast cancer who received epirubicin and cyclophosphamide followed by docetaxel (EC-T), expressions of S100A6 and MDM2 were negatively correlated, and high expression of S100A6 suggested a higher rate of pathologic complete response (pCR)." (PMID 37217945, 2023). "The expressions of S100A6 and MDM2 in patients with invasive breast cancer were analyzed by immunohistochemistry." (PMID 37217945, 2023). "For patients with invasive breast cancer who received epirubicin and cyclophosphamide followed by docetaxel (EC-T), the expressions of S100A6 and MDM2 were negatively correlated, and S100A6 was a predictive biomarker for the efficacy of neoadjuvant chemotherapy." (PMID 37217945, 2023).
invasive ductal carcinoma (1 paper, 2020). "Increased S100A6 expression correlates with increased tumor progression from DCIS to invasive ductal carcinoma." (PMID 32211331, 2020).
lung squamous cell carcinoma (1 paper, 2023). "S100A6 overexpression is closely related to the poor prognosis of lung squamous cell carcinoma and is considered an independent poor prognostic factor for lung squamous cell carcinoma." (PMID 37670392, 2023). "The expression of S100A6 in lung squamous cell carcinoma is significantly correlated with patient age and tumor differentiation." (PMID 37670392, 2023).
metastatic melanoma (1 paper, 2020). A melanoma that has spread from its primary site to another anatomic site. "In another study, gene expression analysis in 45 metastatic melanoma and 20 benign nevi indicated significantly higher levels of S100A6 in metastatic melanoma than in benign nevi." (PMID 33256110, 2020).
metastatic tumors (1 paper, 2011). "S100-A4 and S100-A6 have attracted significant attention because of their established significance in the progression of metastatic tumors." (PMID 21637840, 2011).
multiple sclerosis (1 paper, 2023). A progressive autoimmune disorder affecting the central nervous system resulting in demyelination. "In general, it can be concluded that increase of the expression of LASP1 and S100A6 genes and decrease the expression of the TUBA1C gene in multiple sclerosis disrupts NFAT transcriptional activity." (PMID 36970516, 2023).
myelofibrosis (1 paper, 2024). A partial or complete replacement of the bone marrow stroma by fibrous tissue. "When we looked for genes which were differentially expressed in the key interacting cell types in myelofibrosis, only two genes were concordantly dysregulated across cell types – S100a6 and Lgals1." (PMID 39383242, 2024).
myeloid leukemia (1 paper, 2020). A clonal proliferation of myeloid cells and their precursors in the bone marrow, peripheral blood, and spleen. "However, to develop targeting of S100A6 for treatment of myeloid leukemia, it is essential to understand how loss of S100A6 affects normal blood development." (PMID 32555370, 2020).
myeloid malignancies (1 paper, 2024). "A role for S100a6 and other S100 family members in inflammation and malignant hematopoiesis has previously been reported, whereas galectin-1 has not been extensively studied in myeloid malignancies." (PMID 39383242, 2024).
nasopharyngeal carcinoma (1 paper, 2023). A carcinoma arising from the nasopharyngeal epithelium. "Increased p38, but not ERK1/2, phosphorylation was also detected after S100A6 overexpression in nasopharyngeal carcinoma cells, while an adverse effect was observed after S100A6 silencing." (PMID 36674873, 2023).
nonalcoholic fatty liver disease (1 paper, 2025). "As for S100A6, a member of the S100 family of calcium-binding proteins, has been reported to be associated with T2DM development, contributing to hepato-pancreatic communication to reduce insulin production and promote the progression of T2DM in individuals with nonalcoholic fatty liver disease." (PMID 39850446, 2025).
pilomatrixoma (1 paper, 2021). Pilomatrixoma is a rare and benign hair cell-derived tumor occurring mostly in young adults (usually under the age of 20) and characterized as a 3-30 mm solitary, painless, firm, mobile, deep dermal or subcutaneous tumor, most commonly found in the head, neck or upper extremities. "Diseases associated with S100A6 include Pilomatrixoma and Retinitis Pigmentosa." (PMID 34530774, 2021).
preeclampsia (1 paper, 2021). Preeclampsia is a hypertensive disorder of pregnancy that is characterized by new-onset hypertension with proteinuria presenting after 20 weeks of gestation, and depending on mild or severe forms may initially present with severe headache, visual disturbances, and hyperreflexia. "Significant expression of S100A6 was observed also in placenta of women diagnosed with preeclampsia, and its expression is increased in oxidative stress response." (PMID 34063287, 2021).
prostatic adenocarcinoma (1 paper, 2004). "Immunostaining for S100A6 showed that in all 66 cases of benign epithelium adjacent to prostatic adenocarcinoma, the staining was seen to be intense in the nuclei and cytoplasm of basal cells, with luminal cells showing an absence of staining." (PMID 15280928, 2004). "In neuronal cell lines it has been shown that S100B may form heterodimers with S100A6 and that S100B protein expression is co-localised with S100A6, we therefore performed immunostaining for S100B in 20 cases of organ confined prostatic adenocarcinoma with adjacent benign epithelium." (PMID 15280928, 2004). "In all cases of prostatic adenocarcinoma (matched), metastatic lesions and 3/10 high-grade prostatic intraepithelial neoplasia lesions, an absence of S100A6 was seen." (PMID 15280928, 2004).
renal cell carcinoma (1 paper, 2016). "In renal cell carcinoma cells, knockdown of calcium-regulating S100A6 suppressed cell growth via induction of G2/M phase arrest, a finding that has previously been reported in other cell types, and significantly reduced tumor mass in an in vivo mouse model." (PMID 27709523, 2016). "Furthermore, S100A6 knockdown activated CXCL14-induced apoptosis in a renal cell carcinoma cell line." (PMID 27709523, 2016).
rheumatoid arthritis (1 paper, 2023). A chronic, systemic autoimmune disorder characterized by inflammation in the synovial membranes and articular surfaces. "Our results point out that the detection of S100A6 in tear samples seems to be positively correlated to rheumatoid arthritis, consistent with the systemic nature of this autoinflammatory pathology." (PMID 37185712, 2023).
Senile plaques (1 paper, 2019). Senile plaques are extracellular deposits of amyloid in the gray matter of the brain. "In addition, the expression of S100A6 around senile plaques was increased along with the increases of Aβ deposition." (PMID 31440382, 2019). "In addition, the intensity of Aβ-immunoreactive senile plaques was reduced (P < 0.01, d1) and S100A6 staining nearly disappeared in the CQ treatment group (d2)." (PMID 31440382, 2019). "Boom and colleagues observed that S100A6 clusters were correlated to the density of Aβ-associated senile plaques, whereas the effect of S100A6 overexpression in zinc levels is not clear yet." (PMID 31440382, 2019).
Sepsis (1 paper, 2025). Sepsis is defined as life-threatening organ dysfunction caused by a dysregulated host response to infection. "Another member of the S100 family, S100A6, contributes to the cytokine storm that characterizes sepsis by being linked to stress and inflammatory reactions." (PMID 41303672, 2025). "Members of the S100 protein family, S100A8, S100A9 and S100A6 are essential to the pathophysiology of sepsis." (PMID 41303672, 2025).
thyroid tumor (1 paper, 2023). A benign or malignant neoplasm affecting the thyroid gland. "S100A6 and S100A2 are also associated with the progression of thyroid tumors." (PMID 37670392, 2023).
tumor (117 papers, 2004 to 2026). "Cluster 1 expressed S100a4, S100a6, and Spp1, genes associated with tumor progression and metastasis." (PMID 41567211, 2025). "S100 family members such as S100A8, S100A9, S100A13, and S100A6 are upregulated in advanced BC and are associated with tumor progression, immune suppression, and poor prognosis." (PMID 41404073, 2025). "Since S100A6, which was implicated in tumor progression in several other cancers, can either act on MG in a cell-restricted manner or can be secreted, elevated expression levels of S100A6 and other S100 members need further examination." (PMID 34539650, 2021). "S100a6 can be secreted from several tumor cell types, and has been implicated in regulation of cell cycle and CXCL14, a pro-inflammatory chemokine." (PMID 32785175, 2020). "A significant association between Duke's tumour stage, lymphatic invasion, and S100A6 expression was confirmed." (PMID 26880885, 2016). "When tumors were further sub-divided based on the maximum diameter of tumors, we found that the expression of S100A6 was positively associated with the tumor diameter." (PMID 25760073, 2015). "We have previously reported that glyphosate potentially causes tumor promotion in two-stage mouse skin carcinogenesis model, and S100A6, S100A9 (Ca2+-regulating proteins), SOD 1 (oxidative stress-related protein) are associated with this tumor promotion." (PMID 24073338, 2013). "Previously, we have reported that glyphosate potentially causes tumor promotion in mouse skin carcinogenesis and S100A6, S100A9, and SOD 1 are associated with this tumor promotion." (PMID 24073338, 2013). "S100A6 expression, particularly when associated with osteopontin, another pro-metastatic protein and high a-fetoprotein levels, are associated with poor tumor differentiation." (PMID 23166536, 2012). "S100A6 is closely associated with the prognosis and malignancy of many tumor diseases." (PMID 37670392, 2023). "S100A6 not only plays a role in the differential diagnosis, prognosis, and malignant degree prediction of tumor diseases but is also a diagnostic and monitoring indicator of some tumor diseases." (PMID 37670392, 2023). "In the same study, a tendency toward the same evolution was observed for S100A4, while two other proteins in the S100 family, encoded by the S100a6 and S100a11 genes, exhibited a similar increase in untreated tumor-bearing rats, which was completely reversed upon curcumin treatment." (PMID 35873564, 2022). "As indicated by the previousstudies, S100A6 is associated with tumorigenesis and tumor progression, promoting theproliferation and migration of human colorectal cancer cells, HCC cells, andosteosarcoma cells and epithelial–mesenchymal transition (EMT) of pancreaticcancer cells." (PMID 33335992, 2020). "In the present study, we have extended the value of S100A6 to include it as an OVCA serum biomarker by demonstrating positive expression in human OVCA using immunohistochemistry, as well as an association between S100A6 serum level and tumor burden in both mice and human patients." (PMID 19888321, 2009). "S100A6 methylation showed a statistically significant association with the large cell/anaplastic histopathological morpho-phenotype (50%; (3 out of 6) of large cell/anaplastic tumours vs 8% (2 out of 25) of classic and 0% (0 out of 9) of nodular/desmoplastic tumours; P=0.026 by Fisher's exact test)." (PMID 17579622, 2007). "The role of S100A6 is well established across multiple tumour types where increased S100A6 expression contributes to tumourigenesis and worse patient outcome." (PMID 41673585, 2026). "We constructed a spatial transcriptomic map of CRC development and further defined molecular differences between tumor and normal tissues, as well as differences validated, in part, through known cell markers like S100A6 and CLU." (PMID 41009818, 2025).
tumor (continued). "In contrast, other S100 proteins such as S100A6, S100A8, S100A9, and S100A11 are frequently upregulated in various malignancies, including BC, where they are linked to tumor-promoting functions." (PMID 41404073, 2025). "In total, 469 genes exhibited higher expression levels in tumor tissues compared to normal tissues, including S100A6 and S100A4." (PMID 40723292, 2025). "Another gene set was the S100 family including S100A11, S100P and S100A6, which mediate tumor progression and metastasis through their roles in cell motility, invasion, and angiogenesis." (PMID 40018643, 2025). "Among these identified targets, S100A6, a member of the calcium‐binding protein family, is found to be expressed in certain tumor cells." (PMID 39375892, 2025). "S100A6, a calcium-binding protein of the S100 family, localizes primarily to the cytoplasm of tumor cells, while CLU, a multifunctional protein, is significantly upregulated under cellular stress in diseases including cancer." (PMID 41009818, 2025). "S100A6 exists in various mammalian tissues and cells and is closely related to many neoplastic diseases, such as lung cancer, colorectal cancer, pancreatic cancer, melanoma, and liver cancer." (PMID 38877413, 2024). "These alignment findings validated the robustness of the single-cell classification and underscored the EMT-subtype tumor cell marked by S100A6 as the subtype with high metastatic potential." (PMID 39095854, 2024). "MZT2A is a key gene involved in mitotic spindle formation and promotes cell proliferation, while S100A6 and S100P are well-known marker genes for tumor cells." (PMID 39883515, 2024). "S100A6 has several molecular functions related to apoptosis and differentiation, and tumor invasion, migration, and proliferation." (PMID 38877413, 2024). "By elucidating the features and evolutions of the three subtypes in HCC, we identified and characterized the tumor cells with high metastatic potential and confirmed S100A6 as the biomarker." (PMID 39095854, 2024). "The colocalization of CCN2/TGF-β/TGFBR1 in the membrane of S100A6+ tumor cells further confirmed the interaction pair." (PMID 39095854, 2024). "Among them, the S100A6+ tumor cells, designated EMT-subtype, have exhibited a strong association with metastasis, indicating a potential key player in the aggressive behavior of HCC." (PMID 39095854, 2024). "mIF images visualized the spatial proximity of S100A6+ TGFBR1+ tumor cells and FAP+ CCN2+ fibroblasts." (PMID 39095854, 2024). "S100A6 is a Ca2+-binding protein expressed in a limited number of cell types in normal adult tissues and several tumor cell types." (PMID 38877413, 2024). "Recent studies have shown that S100A6 is abnormally expressed in various tumor lesions, such as melanoma, lung, colorectal, pancreatic, and liver cancers." (PMID 37670392, 2023). "Cell differentiation and proliferation are closely related, whereas S100A6 and cell proliferation are often related to tumor diseases." (PMID 37670392, 2023). "Given the in vitro observations, suppression of S100A6 on tumor development and its enhancement on sensitivity to paclitaxel were investigated in a nude mouse xenograft model." (PMID 37217945, 2023). "Most importantly, in many studied cases, a positive correlation between S100A6 expression and the disease stage, tumor size and/or metastasis has been reported." (PMID 36674873, 2023). "In vivo, S100A6 also suppressed the tumor growth and enhanced its sensitivity to paclitaxel in a nude mouse xenograft model." (PMID 37217945, 2023). "The serum concentration of S100A6 was found to be related to the experimental tumor load and clinical disease stage." (PMID 37670392, 2023). "S100A6 is expressed in various tumor diseases, and variations in its expression in different diseases and at different stages of disease development make it a biomarker for disease diagnosis, differentiation, and prognosis evaluation." (PMID 37670392, 2023).